RNU6-260P (RNA, U6 small nuclear 260, pseudogene)
Gene: Small nuclear RNA gene on chromosome 5 (157,809,098 to 157,809,204, forward strand). Ensembl gene ENSG00000206819.
Homologues: Orthologues: chimpanzee U6 (99% identical), macaque U6 (93% identical), mouse Gm22079 (66% identical), guinea pig U6 (65% identical). Paralogues in human: RNU6-338P (82% identical), RNU6-1011P (81% identical), RNU6-140P (81% identical), RNU6-38P (81% identical), RNU6-971P (81% identical), RNU6-1029P (80% identical), RNU6-1117P (80% identical), RNU6-1122P (80% identical), RNU6-1124P (80% identical), RNU6-246P (80% identical), RNU6-49P (80% identical), RNU6-73P (80% identical), and 1285 more.